RN7SKP50 (RN7SK pseudogene 50)
Gene: Miscellaneous RNA gene on chromosome 11 (9,680,924 to 9,681,238, forward strand). Ensembl gene ENSG00000201564.
Homologues: Orthologues: chimpanzee 7SK (99% identical), mouse Gm55200 (66% identical). Paralogues in human: 7SK (76% identical), RN7SKP187 (75% identical), RN7SKP255 (75% identical), RN7SKP176 (74% identical), RN7SKP186 (74% identical), RN7SKP78 (74% identical), RN7SKP71 (73% identical), RN7SKP217 (73% identical), RN7SKP237 (73% identical), RN7SKP118 (73% identical), RN7SKP133 (73% identical), RN7SKP203 (73% identical), and 284 more.